CTLA4 (cytotoxic T-lymphocyte associated protein 4)
Diseases named in the same sentence as CTLA4 in open-access papers (continued):
Sharing a sentence is not in itself a finding about the gene and the disease.
ovarian carcinoma (continued). "Recent researches show that common immune checkpoint inhibitors such as PD-1/PD-L1 and CTLA-4 are only effective in patients with advanced/recurrent ovarian cancer, but the clinical efficacy is very limited." (PMID 35991556, 2022). "Dual blockade of PD-1 and CTLA-4 enhanced efficacy of the GVAX vaccine in ovarian cancer models through activation of CD4 and CD8 T cells, secretion of cytokines, and inhibition of Treg cells." (PMID 36275669, 2022). "CTLA-4 measured in serum should be considered as a potential biomarker in the diagnosis of ovarian cancer." (PMID 35054356, 2022). "FANCE positively correlated with immune checkpoint inhibitors PD-1, PD-L1, and CTLA4 in endometrial cancer and ovarian cancer." (PMID 36685883, 2022). "For instance, the treatment of PD-1 antibody Nivolumab, PD-L1 antibody Avelumab, PD-1 antibody Pembrolizumab, and CTLA-4 blocking antibody MDX-CTLA4 only yielded objective response rates (ORR) up to 15% in epithelial ovarian cancer (EOC)." (PMID 35804934, 2022). "A recent trial compared (a) the anti-PD-1 agent nivolumab alone with (b) nivolumab plus the anti-CTLA-4 agent ipilimumab in 100 patients with recurrent or persistent ovarian cancer." (PMID 35838045, 2022). "The cut-off values for PD-1, PD-L1, and CTLA-4 that were elevated in the serum of patients with ovarian cancer were calculated using ROC curve analysis." (PMID 35054356, 2022). "Low expression of immune checkpoint PD-1 (PLDCD1) and CTLA4 were observed, suggesting poor immune checkpoint blockade status, which is consistent with the low sensitivity of ovarian cancer to immune checkpoint therapy." (PMID 36248860, 2022). "We conclude that CTLA-4 should be considered as a potential biomarker in the diagnosis of ovarian cancer." (PMID 35054356, 2022). "Although immune checkpoint blocking monoclonal antibodies such as PD-1, PD-L1 and CTLA-4 have shown significant prospects in some cancers, the treatment response of ovarian cancer still remains unsatisfied." (PMID 36585688, 2022). "For instance, in chemoresistant ovarian cancer, miR-424 has been proved to regulate the PD-1/PD-L1 and CTLA-4/CD80 pathways." (PMID 33806327, 2021). "In the past few years, immune-checkpoint inhibitors which target immune-checkpoint pathways including cytotoxic T lymphocyte-associated protein 4 (CTLA-4) and PD-1/PD-L1 have been developed in advanced ovarian cancer." (PMID 34063568, 2021). "Particularly, single-agent Abs against CTLA-4, PD-1 or PD-L1 revealed modest results in epithelial ovarian cancer with median response rates (RR) less than 15% and a control of disease rate less than 50%." (PMID 33672017, 2021). "The blockade of PD-1/CTLA-4/LAG-3 can efficiently inhibit ovarian cancer metastasis, thus showing a favorable outcome in reducing the risk of tumor metastasis." (PMID 34367975, 2021). "We also observed a strong correlation between ICOS and CTLA-4 in both our cohort (r = 0.8913, p < 0.0001) and the TCGA ovarian cancer cohort (r = 0.9093, p < 0.0001)." (PMID 33747935, 2021). "In the microenvironment of ovarian cancer, the engagement of co-inhibitory immune checkpoint molecules such as CTLA-4 can lead to the inactivation of TILs." (PMID 32127601, 2020). "The antibody blocking of CTLA-4 or PD-1 alone is promising treatment for some categories of advanced disease endometrial cancer, but it has little effect against ovarian cancer." (PMID 33182298, 2020). "Here we report the clinical outcome of combining ACT with both CTLA-4 and PD-1 blockade in ovarian cancer patients." (PMID 32547707, 2020). "The anti-CTLA4 antibody ipilimumab has also been tested in ovarian cancer patients, claiming an ORR of 10.3% in a still unpublished trial (NCT01611558)." (PMID 32547707, 2020). "In conclusion, we show that targeting CTLA-4 within the initial tumor fragment cultures for ACT in ovarian cancer, increases TIL proliferation and favors the expansion of tumor-reactive CD8+ TILs." (PMID 32127601, 2020).
ovarian carcinoma (continued). "Recently, immune checkpoint inhibitors such as those targeting CTLA-4, PD-1, or PD-L1 have been used to treat ovarian cancer." (PMID 33282553, 2020). "Tremelimumab is another anti-CTLA-4 mAb in clinical development and trialled in ovarian cancer patients in conjunction with poly (ADP-ribose) polymerase (PARP) inhibitors." (PMID 32937961, 2020). "A similar observation has been reported in a model of ovarian cancer in which therapeutic co-blockade of PD-1/LAG-3/CTLA-4 in WT mice leads to two times fewer tumor free mice compared to anti-LAG-3/CTLA-4 treatment in PD-1-/- mice." (PMID 33519801, 2020). "A mouse model of ovarian cancer has shown that in vivo treatment with single agent antibodies against PD-1, CTLA-4, or LAG-3 leads to compensatory upregulation of other checkpoint inhibitor pathways in tumour-associated lymphocytes." (PMID 32937961, 2020). "Ipilimumab, which blocks CTLA-4, was used in a phase II study as a single agent for patients with platinum-sensitive ovarian cancer (NCT01611558)." (PMID 30646939, 2019). "The expression of CTLA-4 was highest in type I ovarian cancer followed by type II, and was lowest in type III ovarian cancer." (PMID 32793247, 2018). "Immune checkpoint blockade (ICB), mainly anti-CTLA-4 and anti-PD-1/PD-L1 therapy, has showed promising clinical benefits in the treatment of some cancer types; however, its application in ovarian cancer is still in the primary stage." (PMID 32793247, 2018). "The expression level of these genes was increased in type I and II ovarian cancer, indicating an appropriate microenvironment for anti-CTLA-4 and anti-PD-1/PD-L1 therapy." (PMID 32793247, 2018). "TNFR2+ Tregs conditioned in ovarian cancer ascites, compared to media, also expressed higher levels of functional immunosuppressive molecules such as PD-L1, CTLA-4, and GARP." (PMID 29163543, 2017). "Anti-CTLA4 antibodies (ipilimumab) have been administered to ovarian carcinoma patients after vaccination with irradiated, autologous tumor cells engineered to secrete GM-CSF." (PMID 28275576, 2017). "The combination of OX40 and anti-CTLA-4 is synergistic in ovarian carcinoma (ID8), fibrosarcoma (MCA-205), and prostate cancer (TRAMP1) models." (PMID 27847783, 2016). "Several antibodies directed against PD-1, PD-L1, and CTLA-4 have been developed and are being tested clinically in patients with ovarian cancer." (PMID 27904752, 2016). "In the ID8 ovarian cancer model, tumor-infiltrating Tregs – which express both CTLA-4 and PD-1 – are reduced upon CTLA-4 and PD-1 dual blockade coinciding with increased tumor-infiltrating CD8+ T cells." (PMID 26500653, 2015). "Therapies targeting CTLA-4 have also been investigated in ovarian cancer; a combined treatment, which involves blockade of CTLA-4 and PD-1 and boosts the immune system, was found to induce tumor rejection in 75% of tumor models examined." (PMID 25478323, 2014). "Moreover, low risk score was associated with higher IPS of anti-CTLA4, anti-PD1 and anti-CTLA4/PD1 in ovarian cancer patients (p < 0.05)." (PMID 37784081, 2023). "Furthermore, in murine ovarian cancer, a combination of anti-CTLA4 with decitabine potentiated the efficacy of anti-CTLA4 as it enhanced T cell activity." (PMID 36672677, 2023). "Notably, the S01 NK cell state was significantly lower in the PTGS2/CTLA4-high group in the TCGA ovarian cancer dataset." (PMID 38201508, 2023). "In addition to the well-studied PD-1, PD-L1 and CTLA-4 in ovarian cancer, the role of TIM-3 and LAG-3 expression seems promising." (PMID 36359346, 2022). "This study was designed to investigate whether PD-1, PD-L1, and CTLA-4 proteins measured in serum can be used to diagnose ovarian cancer." (PMID 35054356, 2022). "To date, the best-studied immune checkpoints in ovarian cancer have been PD-1, PD-L1 and CTLA-4." (PMID 36359346, 2022). "However, immune checkpoint inhibitors (anti-CTLA-4 or anti-PD-1/PD-L1) have yielded modest clinical results in ovarian cancer patients." (PMID 34359708, 2021).
ovarian carcinoma (continued). "In addition, several checkpoint blocking antibodies, such as those directed against CTLA‐4 and PD‐1, have been developed and are being tested clinically in patients with ovarian cancer." (PMID 32860347, 2020). "In ovarian cancer cell lines and in ovarian cancer tissues, it was reported that the expression of miR-424 negatively correlated to the expression of CTLA-4/CD80 and PD-L1, and that the restoration of miR-424 re-established T cells activity, reverted chemoresistance and increased free survival time." (PMID 32316552, 2020). "Other studies also identify the increase of the lymphocyte infiltration and the T helper 1-type chemokines and cytokines as possible cause of the better observed outcome when de-methylation and anti-PD-L1 and CTLA4 agents are used in combination in a murine ovarian cancer model." (PMID 31968651, 2020). "In addition, in a mouse ovarian cancer model, de-methylation triggers the type I interferon signaling pathway, sensitizing mice to anti-CTLA4 therapy." (PMID 31968651, 2020). "We also propose mechanisms whereby blocking CTLA-4 and PD-1 may be used in combination with other agents to give much better survival in advanced disease ovarian cancer patients." (PMID 33182298, 2020). "We hypothesized that ovarian cancer TILs might be inactivated through co-inhibitory interactions such as the immune checkpoint CTLA-4." (PMID 32127601, 2020). "However, checkpoint inhibitor treatment targeting PD1 and CTLA4 has been tested in ovarian cancer patients with sparse response rates, leaving TIGIT as a remaining potential target for treating HGSC recurrence." (PMID 33352957, 2020). "Preclinical studies support the rationale for combining epigenetic and immune therapies: in a syngeneic ovarian cancer mouse model, a combination of decitabine and anti-CTLA-4 significantly reduced tumor growth and prolonged survival compared to each drug alone." (PMID 30646939, 2019). "In Brca1-deficient mouse models of ovarian cancer for example, inhibition of CTLA-4 but not PD-1/PD-L1 synergised with PARP inhibitor treatment." (PMID 29123260, 2018). "Patients with type I and II ovarian cancer may be more sensitive to anti-CTLA-4 therapy, anti-PD-1/PD-L1 therapy, and a combination of immunotherapies." (PMID 32793247, 2018). "The most prominent limitation is that some type I and II ovarian cancer patients may also be insensitive to anti-CTLA-4 and anti-PD-1/PD-L1 therapy." (PMID 32793247, 2018). "In mouse models of ovarian cancer, 1/3 to 1/2 of TILs coexpressed PD-1 and CTLA-4." (PMID 27904752, 2016). "Indeed, reduction of MDSC suppressive function has been described for CTLA-4 blockade therapy in an in vitro and in vivo murine ovarian carcinoma model." (PMID 26196012, 2014). "Importantly, the ability of NIR-PIT to induce ICD provides a strong rationale for combination with immune checkpoint inhibitors such as anti-PD-1/PD-L1 or anti-CTLA-4 antibodies, which may enhance and prolong anti-tumor responses in ovarian cancer." (PMID 41362788, 2025). "Our results suggest that targeting COX-2 prior to the anti-CTLA-4 immunotherapy scheme, which takes advantage of NK cells cytotoxic capacity, may be a promising strategy to improve the effectiveness of immunotherapy for ovarian cancer patients." (PMID 38201508, 2023). "Similarly, in mouse models of BRCA1-deficient ovarian cancer, PARP inhibition and immune checkpoint inhibition targeting cytotoxic T-lymphocyte-associated protein 4 (CTLA-4) increased T-cell tumor infiltration and interferon-gamma production, improving survival." (PMID 37509318, 2023). "Cyclooxygenase-2 (COX-2) expression causes several changes in the tumor microenvironment (TME) of ovarian cancer, which are associated with a low immunotherapy response in patients and immunosuppression in the TME, mainly due to cytotoxic T-lymphocyte-associated-protein-4 (CTLA-4) expression." (PMID 38201508, 2023).
ovarian carcinoma (continued). "We focused on the expression of symbolic genes CA125 and HE4 and immune checkpoint genes PD-1, PD-L1, PD-L2, and CTLA4 in different groups of ovarian cancer so as to further explore the correlation between histone acetylation and the progress, treatment, and prognosis of ovarian cancer." (PMID 36172179, 2022). "Also, in the ID8-VEGF ovarian carcinoma mouse model, decreased proliferation and the inability of the tumor infiltrating lymphocytes to produce cytokines was attributed to the expression of CTLA-4 and PD-1 makers." (PMID 26802025, 2016). "VISTA, CTLA4, PDL1, PD1, CD8, CD4, and FOXP3 mRNA extracted from 429 patients with ovarian cancer in the Cancer Genome Atlas (TCGA) database was included as a validation cohort." (PMID 38634058, 2024). "Immunotherapy is currently not an effective treatment for ovarian cancer, but our results suggested that low-risk patients may have the opportunity to respond to certain immunotherapy such as immune checkpoint inhibitors targeting CTLA4." (PMID 38136595, 2023). "The IPS values (IPS-CTLA-4_pos and IPS-PD-1/PD-L1/PD-L2_pos) as the alternative of the ovarian cancer patients’ responses to anti-CTLA-4 and anti-PD-1/PD-L1 treatment were increased in the high TMEscore group." (PMID 35439731, 2022). "Expression of PD-1, CTLA-4, TIM-3 and LAG-3 significantly correlated with infiltrating immune cells in ovarian cancer." (PMID 36359346, 2022). "PD-1 and CTLA-4 inhibitors can modulate the amount and activity of ARG-1, which prevents MDSCs from suppressing the immune system in ovarian cancer." (PMID 36311734, 2022). "We then evaluated correlation of T cell exhaustion biomarkers PD1 (PDCD1), CTLA4, LAG3 and HAVCR2 with the expression of CD47 in ovarian cancer." (PMID 34966389, 2021). "We analyzed the expression levels of the checkpoint receptors in the three ovarian cancer subtypes responsible for decreasing T cell bioactivity, including PDCD1 (PD1), CTLA4, LAG-3, and TIM-3." (PMID 33282564, 2020). "Following irradiation, murine 1D8 ovarian carcinoma cells up-regulate the activation marker CD80 and suppress CD4+CD25+ regulatory T-cells (Tregs) via engagement of CD152 (CTLA-4)." (PMID 30178305, 2018). "Genes related to ICB (CTLA-4, PD-L1, and PD-L2) and cytotoxic lymphocytes (CD8A, GZMA, and PRF1) were all highly expressed in type I and II ovarian cancer." (PMID 32793247, 2018). "Clinical trials of anti-CTLA-4 antibody (NCT02571725), anti-PD-1/PD-L1 antibody (NCT02498600 NCT02674061), or a combination of these (NCT03249142) are undergoing for ovarian cancer." (PMID 32793247, 2018). "To date, the most studied immune escape mechanisms in epithelial ovarian cancer are those related to PD1-PDL1 and CTLA-4." (PMID 29456457, 2018). "Genes related with ICB, including CTLA-4, PD-L2, PD-L1, CD8A, GZMA, and PRF1, were all lowly expressed in type III ovarian cancer." (PMID 32793247, 2018). "Taken together, these results suggest that the interference with the CTLA4 pathway, leading to depletion of Tregs and probably to activation of effector CD8+ T cells, is involved in the control of ovarian carcinoma to some extent." (PMID 28275576, 2017). "Moreover, there is a strong correlation between immune cell infiltration and the expression of PD-1, CTLA-4, TIM-3, and LAG-3 in the ovarian cancer microenvironment." (PMID 40649775, 2025). "A new- checkpoint V-domain Ig-containing suppressor of T cell activation (VISTA) has appeared, but the use of its inhibition effect in combination with antibodies targeting PDL1/PD1and CTLA4 has not been reported in ovarian cancer." (PMID 38634058, 2024). "We found that the total count of activated NK cells (estimated by MIXTURE) was higher only in the PTGS2/CTLA4-low group from the ovarian cancer TCGA cohort, but not for the AOCS cohort." (PMID 38201508, 2023).
ovarian carcinoma (continued). "We next observed that SPP1 expression was positively related with immune-checkpoint, such as CD274, CTLA-4, LAG3 and TIGIT, suggesting that SPP1 may play an important role in immune tolerance of ovarian cancer." (PMID 36585688, 2022). "Immune‐checkpoint molecules PD‐1, LAG3, CTLA4, TIGIT, and HAVCR2 (TIM‐3) have been identified and studied in various cancers including liver hepatocellular carcinoma, lung adenocarcinoma, stomach adenocarcinoma, ovarian cancer, and peritoneal carcinoma." (PMID 35184420, 2022). "A recent retrospective analysis of epithelial ovarian cancer patients receiving ICB immunotherapy of targets including PD-1, PD-L1, CTLA-4, and LAG-3 alone or in combination, found that over 50% of patients suffer disease progression requiring early discontinuation of therapy." (PMID 32937961, 2020). "In particular, CTLA-4 and PD1/PD-L1 are important immune checkpoints for ovarian cancer." (PMID 32850861, 2020). "Thus, we have initiated the first clinical study treating patients with ovarian cancer with combinational therapy consisting of ACT, anti-PD1, anti-CTLA4, and anti-LAG3 (ClinicalTrials.gov identifier: NTC04611126)." (PMID 33352957, 2020). "Among them, CTLA-4 and PD1/PD-L1 are important immune checkpoints for ovarian cancer." (PMID 32850861, 2020). "Accordingly, in an ovarian carcinoma-bearing mice model, IFN-γ-stimulated M-MDSC increased MHC class II, CD80, and IL-10 expression, and induced CD4+CD25+ Treg in a CTLA-4/CD80-dependent manner, which is in line with our results on IL-10-producing GM-CSF/IL-6 M-MDSC." (PMID 30936876, 2019). "Dual blockade of both PD-1 and CTLA-4 in combination with tumor vaccine has also been shown to enhance tumor rejection in other mouse tumor models such as CT26 colon carcinoma and ID8-VEGF ovarian carcinoma." (PMID 29072624, 2017). "Besides CTLA4, PD-1- and LAG3-expressing CD8+ T cells specific for tumor-derived antigen NY-EASO-1 were also detectable within the ovarian carcinoma infiltrates." (PMID 28275576, 2017). "On these bases, in a murine ovarian cancer model Higuchi and colleagues demonstrated that the CTLA-4 antibody, but not the inhibition of the PD-1/PD-L1 pathway, synergize with PARP-inhibitors increasing long term survival in the majority of mice (p < 0.0001)." (PMID 27447625, 2016). "Moreover, CTLA-4 blockade has also been found to improve the anti-cancer effect of TILs by increasing TIL proliferation, proportion of CD8 + T cells and TIL immunoreaction, in ovarian cancer cells, compared to co-culture of IL-2 and TILs." (PMID 41024300, 2025). "In recent years, chimeric antigen receptor- and TCR-engineered T cells, immune checkpoint inhibitors (including CTLA-4 and PD-1/PD-L1 inhibitors), cancer vaccines, and oncolytic viruses which would reverse the signals from the TME have been investigated as potential therapies for ovarian cancer." (PMID 36801818, 2023). "The tumor-suppressive microenvironment mediated by Tregs is a significant obstacle to successful immunotherapy, suggesting that depletion of Treg cells, like immune checkpoint blockade of CTLA-4 or PD1/PDL1, could be a potentially effective immunotherapy for ovarian cancer." (PMID 35935940, 2022). "CTLA-4 and PD-1 are expressed in human solid tumor-derived cells, and recent studies have shown that BTLA is expressed in a small subpopulation of cancer cells from clinical tumor specimens mainly identified by immunohistochemical including NSCLC, gastric cancer, and ovarian cancer cells." (PMID 36552785, 2022). "The dual blockade of PD-1 and CTLA-4, conducted to simultaneously inhibit CD276, can help in inhibiting the activation of T cells and cytokine secretion, thereby also downregulating LAG-3 expression and improving antitumor immunity to achieve inhibition of ovarian cancer metastasis." (PMID 34367975, 2021).